G6PD (glucose-6-phosphate dehydrogenase)
Diseases named in the same sentence as G6PD in open-access papers (continued):
Sharing a sentence is not in itself a finding about the gene and the disease.
malaria (continued). "Analysis of the distribution of the genetic factors that have been shown to influence malaria outcome (sickle cell trait, G6PD and alpha thalassemia) also did not reveal any significant differences between the two groups." (PMID 28427357, 2017). "Assays to detect G6PD that can be run in the field without elaborate equipment will be necessary to optimally treat malaria-infected individuals." (PMID 28552983, 2017). "While other studies have shown similar results in healthy volunteers, a recent study in Brazil found that the sensitivity of the CareStart G6PD RDT dropped to 50% in patients with malaria compared to 80% in those who did not." (PMID 28542194, 2017). "The present study was aimed in determining allelic frequency of G6PD c.563C>T in male individuals with or without malaria by using archived DNA samples." (PMID 29065882, 2017). "The frequencies of HBB, G6PD, and NOS2 polymorphisms of children lacking malaria symptoms throughout the year and those showing malaria symptoms were statistically similar." (PMID 28793894, 2017). "Alongside the lack of G6PD testing, under-resourcing and poor security hamper the control of malaria." (PMID 27708189, 2016). "The current study followed national malaria treatment guidelines, which do not dictate that G6PD testing must be conducted prior to PQ administration." (PMID 27176722, 2016). "The Bangladeshi national treatment guidelines for uncomplicated malaria follow WHO recommendations but without G6PD testing prior to primaquine administration." (PMID 27128675, 2016). "The guidelines recommend that patients with confirmed P. vivax or P.ovale malaria who are not aware of their G6PD status should be tested before the administration of radical cure with primaquine." (PMID 26911803, 2016). "The reason for this difference in protection is not clear, as it is not known how malaria parasites are affected by RBCs that lack G6PD activity." (PMID 27109515, 2016). "In this study we analysed more than 30 G6PD genetic markers in 506 Tanzanian children with severe malaria and 477 without malaria." (PMID 25671784, 2015). "There were differences in haplotype frequencies between the ethnic groups, and association analysis did not reveal strong evidence of protective G6PD genetic effects against uncomplicated malaria in both ethnic groups and gender." (PMID 25015414, 2014). "Therefore, there is a need to evaluate the test characteristics of the CareStart G6PD RDT by the users of this PoC, such as health facility staff and village malaria workers (VMWs)." (PMID 25541721, 2014). "There are differences in haplotype frequencies between Dogon and Fulani, and association analysis did not reveal strong evidence of protective G6PD genetic effects against uncomplicated malaria in both ethnic groups and gender." (PMID 25015414, 2014). "In a traditionally malaria-endemic area of South-eastern Brazil, the frequency of G6PDd and average G6PD activity was similar between the groups with and without a history of malaria." (PMID 24568147, 2014). "The percentage of G6PD A hemizygous males harboring malaria parasites was not statistically different from those with the wild type G6PD (42.6% versus 42.1%, OR 0.98 (95% CI 0.37 – 2.55), p = 0.9." (PMID 24943486, 2014). "While primaquine administration without G6PD screening for confirmed malaria cases is thought to be relatively common, ethical issues regarding the use of the drug are regaining attention as wider community use is considered." (PMID 23782846, 2013). "The G6PD status and the outcomes of severe malaria in children with and without haemoglobinuria was studied with respect to renal failure, the recurrence of haemoglobinuria and blood pressure changes over a three-month follow-up period." (PMID 23039275, 2012). "The current study selected for particular malaria patients, so it is not surprising that G6PD gene frequencies are divergent from those reported for randomly selected healthy individuals in the general population." (PMID 21849081, 2011).
malaria (continued). "Malaria, study site, sickle cell disease, G6PD or hookworm infection did not significantly predict post-discharge death." (PMID 18682797, 2008). "However, a comparison of G6PD activity between children diagnosed with malarial anaemia and those with malaria without anaemia showed significantly lower enzymatic activity in P. falciparum infected children with anaemia compared to those without anaemia." (PMID 41050847, 2025). "Finally, the usual follow-up of patients did not include a G6PD assay several months after the malaria episode, although it would have been very useful to determine the true basal levels in the included patients." (PMID 38725027, 2024). "Importantly, G6PD status was not previously considered within malaria case management and so was completely unfamiliar to HCPs." (PMID 38837977, 2024). "In addition, a study assessing 7 day PQ adherence in the Peruvian Amazon found that after patients completed ACT, malaria symptoms were often abated such that patients lacked motivation to travel for G6PD testing and further treatment." (PMID 38395925, 2024). "Furthermore, it did not include a control group (i.e. malaria-free controls) to compare changes in G6PD activity in the absence of malaria infection." (PMID 38725027, 2024). "Similarly, evaluation of the same quantitative G6PD test used in the current study prior to primaquine showed that HCPs and patients did not always associate AHA signs and symptoms with malaria treatment." (PMID 38837977, 2024). "Finally, two23, 29 of six14, 21, 23, 29, 30, 32 studies that measured quantitative G6PD activity assessed activity during convalescence rather than the acute malaria episode." (PMID 37748497, 2024). "That said, referral hospital staff, who see fewer malaria cases and do not frequently perform the G6PD test nor administer treatment, did show fear that primaquine could cause a negative health impact on patients (etd3, rhl2)." (PMID 39028699, 2024). "Additionally, the co-infections/defects of malaria*HIV*sickling (0.03%), HIV*syphilis (0.01%), syphilis*sickling (0.09%), hepatitis B*syphilis (0.04%), and hepatitis B*HIV (0.01%) were detected in women with normal G6PD." (PMID 37568487, 2023). "However, most study participants did not have the knowledge that G6PD testing was necessary before taking any malaria medicines, particularly PQ." (PMID 37438774, 2023). "The slow uptake of similar PoC or RDTs such as those for malaria, HIV, and tuberculosis (TB) provide important lessons on the broader societal considerations that are often neglected, including economic implications for widescale implementation of the STANDARD G6PD or other PoC G6PD diagnostics." (PMID 37242320, 2023). "However, the policy was not updated in Haiti where single-dose primaquine (0.75 mg base/kg) is administered to malaria cases under direct observation without G6PD testing." (PMID 36191877, 2022). "However, G6PD screening is not routinely performed, particularly in small malaria clinics along Thailand’s borders." (PMID 36508454, 2022). "Selected patients with uncomplicated malaria were recruited in Bangladesh (n = 87), Indonesia (n = 75), and Ethiopia (n = 173); G6PD activity was measured at the initial presentation with malaria and a median of 176 days later (range 140 to 998) in the absence of malaria." (PMID 35544453, 2022). "For G6PD-deficient males and females (<30% activity), the sensitivity and specificity of the STANDARD G6PD Test was slightly higher among malaria-positive participants as compared to malaria-negative participants on both capillary and venous specimens." (PMID 34383774, 2021). "G6PD activity was compared between individuals with and without malaria diagnosed by microscopy, rapid diagnostic test (RDT), or polymerase chain reaction (PCR), and in aparasitemic participants with and without a history of malaria." (PMID 33891581, 2021).
malaria (continued). "A few days after malaria treatment, the haemoglobin level drop could be mainly due to haemolysis of parasitized red blood cells regardless of the patient’s G6PD status." (PMID 34627236, 2021). "The proportions of G6PD Med male hemizygotes and female heterozygotes were substantially lower in patients with acute vivax malaria than in people incidentally visiting clinics or vaccination centres who did not have malaria." (PMID 33543710, 2021). "Thus, this study is limited to inferring the distribution of G6PD level between non-malaria and malaria-infected samples rather than the rate of malaria infection between normal and low G6PD individuals." (PMID 31590661, 2019). "However, in almost all health facilities in the country, the G6PD status of P. vivax-infected malaria patients is not or cannot be determined at present, leading to non-use of primaquine." (PMID 31525211, 2019). "In malaria-endemic countries, G6PD testing at the 30% threshold can now be achieved using point-of-care qualitative and quantitative rapid diagnostic tests, which could allow for the widespread delivery of a safe and effective short-course primaquine regimen." (PMID 31327563, 2019). "The G6PD*A (A376G) mutation observed in the study is a common variant, resulting in close to normal (~ 85%) enzyme activity of a non-deficient person, without significant clinical manifestations of G6PD-related haemolysis or appearing to confer resistance to malaria." (PMID 30367627, 2018). "However, diagnosis of G6PD status in malaria patients before PQ prescription is not generally conducted in the country." (PMID 29548282, 2018). "The G6PD prevalence among malaria patients was lower than in non-infected persons (p < 0.05)." (PMID 30286752, 2018). "While it is not possible to determine whether Hb level drops in these individuals were due to malaria parasite infection or to SLD-PQ, the results suggest that SLD-PQ is well tolerated in G6PD-d individuals with and those without malaria." (PMID 29342267, 2018). "This study has another limitation in that G6PD enzyme activity in malaria patients could not be checked due to technical limitation in performing enzyme assay in the field using fresh blood samples." (PMID 29548282, 2018). "However, G6PD genotype or phenotype is unlikely to influence the anti-malarial efficacy of other anti-malaria drugs, including combination therapy with artemisinin-based drugs." (PMID 29548282, 2018). "Although none of the malaria endemic countries in the Americas has currently as policy a requirement for G6PD testing prior to PQ administration, Brazil is currently considering to introduce a recommendation to test, whenever possible, for a P. vivax diagnosis before PQ treatment." (PMID 28676055, 2017). "However, many malaria endemic countries have not mandated routine glucose-6-phosphate dehydrogenase (G6PD) testing before initiating PQ for radical cure of patients infected by P. vivax malaria." (PMID 28750669, 2017). "However, primaquine cannot be prescribed for vivax malaria patients at the health centers because in the treatment guideline of malaria in the Lao PDR, not only the G6PD test but also hematocrit and hemoglobin tests are required before prescribing primaquine for vivax malaria patients." (PMID 29261647, 2017). "However, more information is needed about G6PDd prevalence in malaria endemic areas in Colombia, and other endemic countries of the Latin American region, including additional variants not evaluated in this study that may be associated with G6PDd in 20 individuals with no identified G6PD alleles." (PMID 27225440, 2016). "Importantly, G6PD prevalence maps are limited by the quality of screening methods employed, and prevalence maps are unlikely to be useful to malaria programme managers unless they achieve very high resolutions." (PMID 25971688, 2015).
malaria (continued). "The classical genetic markers involved in malaria resistance, such as haemoglobin C (HbC) and S (HbS) (in the HBB gene), glucose-6-phosphate dehydrogenase (G6PD) and blood group polymorphisms, are not sufficient to explain the differences between Fulani and Dogon." (PMID 24098393, 2013). "Thus, according to recent data, cases of submicroscopic malaria in pregnant women do not have large enough changes in hematological parameters for there to be an increase in G6PD activity in submicroscopically infected women that would substantially change the data in our statistical analysis." (PMID 37568487, 2023). "We did not evaluate the interpretation of the G6PD results by the HPH staff nor whether increased frequency of VHV follow-up would have led to increased adherence to the malaria medicines but would be important future research to possibly increase acceptability of and adherence to RDA." (PMID 37438774, 2023). "National malaria treatment guidelines recommend a range of PQ regimens, for example Afghanistan recommends combination of CQ × 3 days + PQ 0.25 mg/kg daily for 14 days but due to absence of G6PD tests uses 0.75 mg/kg weekly PQ for 8 weeks, the equivalent of 45 mg/week in a 60 kg individual." (PMID 33757538, 2021). "Correlation by linear regression of the STANDARD G6PD Test’s G6PD values compared to the spectrophotometric reference assay found that, for capillary specimens, the R-squared correlation value was 0.53 for malaria-negative participants as compared to 0.57 for malaria-positive participants." (PMID 34383774, 2021). "This could have an important ripple effect within families and communities in malaria-endemic settings, whereby more individuals seek testing (possibly independent of a malaria episode), learn their G6PD status, and use this information for decisions beyond malaria treatment." (PMID 32766454, 2020). "A total of 574 malaria cases (severe malaria anaemia, SMA = 137 and non-SMA = 437) seeking treatment at Vihiga County and Referral Hospital in western Kenya, were enrolled and screened for ABO blood group, G6PD deficiency and haemoglobin genotyped in a hospital-based cross-sectional study." (PMID 32646433, 2020). "For the CareStart G6PD RDT to efficiently work in real-life conditions, it was also critical to assess whether capillary samples performed equally well compared to the venous blood samples, as capillary samples are taken for slide preparation and malaria RDTs by health workers." (PMID 25541721, 2014). "Malaria RDT-negative participants were significantly older than malaria patients (p < 0.001), but neither G6PD activity nor Hb readings differed significantly between both cohorts (p > 0.05)." (PMID 36986323, 2023). "Functional G6PD enzyme activity is known to protect cells from oxidative damage through activities of antioxidants such as glutathione, which might protect infected red blood cells as well as the parasite, but it is not clear how this might promote asymptomatic malaria." (PMID 35291755, 2022). "Ideally, a glucose-6-phosphate dehydrogenase (G6PD) test is required prior to initiating treatment with primaquine, but this may not be feasible in the majority of malaria-endemic countries." (PMID 25069530, 2014).
anemia (143 papers, 2006 to 2026). A reduction in the number of red blood cells, the amount of hemoglobin, and/or the volume of packed red blood cells. "Safety will be assessed in passive and active pharmacovigilance, including post-treatment screening for G6PD-associated hemolysis by assessing for anemia and hematuria in a sample." (PMID 40321759, 2025). "In 1971, Yoshida and colleagues suggested a five-category classification system of G6PD mutations based on the residual enzymatic activity and the severity of the anaemia." (PMID 39457422, 2024). "At an individual level the haemolytic risk depends on the G6PD genotype, the degree of exposure to the putative oxidative 8-aminoquinoline metabolites, and also the degree of pre-existing anaemia." (PMID 38319064, 2024). "For example, in the context of Andean Latin America, there has been a notable decline in the percentage of G6PD trait subtypes associated with inherited anemias, decreasing from 76.3% in 1990 to 64.9% in 2019." (PMID 38079097, 2024). "We furthermore corrected three different mutations (R459L, R198C and S106C) in the gene encoding glucose-6-phosphate dehydrogenase (G6PD) in lymphoblastoid cells (LCLs) derived from patients suffering from anemia." (PMID 37474806, 2023). "Among anemias, the worldwide incidence of sickle cell disease, glucose-6-phosphate dehydrogenase (G6PD) deficiencies, and thalassemia was estimated at 0.61, 7.54, and 0.14 million cases/year in 2017, respectively." (PMID 37780637, 2023). "The multivariate analysis was performed to investigate the association between anaemia and G6PD MahidolG487A, the most common mutation in this study." (PMID 36038921, 2022). "Although primaquine is associated with a transient reduction in haemoglobin levels in G6PD-deficient individuals, haemoglobin levels at clinical presentation are the major determinants of anaemia in these patients." (PMID 36109733, 2022). "This treatment regimen is suggestive of a more beneficial therapeutic option for G6PD-deficient or sickle cell patients who are prone to oxidative stress and anemia." (PMID 36399959, 2022). "G6PD and haemoglobinopathies were associated with 2.44 (95% CI [1.66, 3.60]) and 6.15 (95% CI [3.09, 12.26]) times increased odds of anaemia, respectively." (PMID 32153098, 2022). "Although primaquine is associated with a transient reduction in haemoglobin levels in G6PD-deficient individuals, haemoglobin levels at baseline remain the major drivers for anaemia in these patients." (PMID 36109733, 2022). "This will help patient and care givers in deciding the best and most suitable treatment regimen especially for oxidative stress and anaemia prone patients like sickle cell and G6PD-deficient patients." (PMID 36399959, 2022). "Mild to moderate anaemia was found in 50.0% (14 of 28 cases) of G6PD-deficient individuals and 17.7% (37 of 209 cases) of normal patients (OR = 4.65; CI%: 2.04–10.57, p < 0.001)." (PMID 36038921, 2022). "Nonetheless, there was a significant difference in the prevalence of anaemia among G6PD status on days 3 and 7, with more G6PD normal patients having anaemia on day 3 whereas on day 7 more of G6PD deficient had anaemia." (PMID 35279143, 2022). "Compared with patients with wildtype G6PD after controlling for haemoglobinopathies, G6PD-deficient patients with hemizygous and homozygous G6PD MahidolG487A exhibited anaemia with low levels of haemoglobin (11.16 ± 2.65 g/dl, p = 0.041)." (PMID 36038921, 2022). "The purpose of this study was to report the incidence and characterization of dapsone-associated anemia with normal G6PD function in heart transplant recipients at our center." (PMID 36362606, 2022). "G6PD MahidolG487A was an independent risk factor for anaemia based on age, gender, parasite species, parasite density, PKLRR41Q, thalassaemia, and haemoglobinopathies." (PMID 36038921, 2022).